SMAD9 (SMAD family member 9)
Diseases named in the same sentence as SMAD9 in open-access papers (continued):
Sharing a sentence is not in itself a finding about the gene and the disease.
tumor (19 papers, 2015 to 2025). "In multivariate Cox regression adjusted for age, gender, pathologic T/N/M and tumor stage, SMAD9 remained the independent risk factor for the outcomes of CRC." (PMID 40796704, 2025). "The results showed that, compared to normal samples, HSPA6 and NOTCH3 were dramatically increased, while GPD1L, PKP2, and SMAD9 were dramatically decreased in tumor samples in both the CRC training dataset and the CRC validation dataset (all P < 0.05)." (PMID 40796704, 2025). "Pathways muted in CBD-treated 3xTg-AD relative to untreated 3xTg-AD mice primarily center on the Smad9 gene involved in angiogenesis and tumor development." (PMID 40979532, 2025). "The result demonstrated a significant increase in HSPA6 and NOTCH3 expression, but a significant decreased in GPD1L, PKP2 and SMAD9 in CRC tumor group when compared to those in normal group (all P < 0.001)." (PMID 40796704, 2025). "Afterward, we suppressed SMAD9 expression in vivo and found that SMAD9 knockdown in NB xenografts led to a decreased tumor volume and mass." (PMID 36539767, 2022). "An analysis of public functional genomics data showed that NB tumor viability depended on SMAD9, and its dependency score was potentially correlated with the MYCN amplification status and MYCN expression level." (PMID 36539767, 2022). "The histological analysis indicated that SMAD9 knockdown abolished the tumor microstructure, decreased cell proliferation and increased apoptosis." (PMID 36539767, 2022). "By analyzing the expression of Smad9 in NSCLC tumor tissues using data obtained from the TCGA database, we found that Smad9 was poorly expressed in NSCLC tumor tissue samples." (PMID 33472665, 2021). "The mechanism through which Smad9 promotes tumorigenesis and development remains unclear; however, its expression in tumors is directly proportional to tumor malignancy and inversely proportional to patient prognosis." (PMID 41132724, 2025). "Moreover, compared to normal samples, HSPA6, NOTCH3, and PKP2 were dramatically overexpressed, while GPD1L and SMAD9 were dramatically de-expressed in tumor samples in both the LUAD training dataset and the LUAD validation dataset (all P < 0.05)." (PMID 40796704, 2025). "Moreover, suppression of GATA6 induced expression of the Bmp receptor (Bmpr1b) and rendered these tumor cells more sensitive to exogenous Bmp7 stimulation and downstream Smad9 expression." (PMID 32157212, 2020). "In the CRC tumor group, the expression levels of HSPA6 and NOTCH3 protein were dramatically up-regulated, while GPD1L, PKP2, and SMAD9 protein were dramatically down-regulated (all P < 0.05)." (PMID 40796704, 2025). "Compared to the control group, serum levels of HSPA6 and NOTCH3 were significantly elevated in the CRC tumor group, whereas GPD1L, PKP2, and SMAD9 exhibited a marked decrease." (PMID 40796704, 2025). "Meanwhile, when compared with normal group, the HSPA6, NOTCH3 and PKP2 expression were significantly increased in LUAD tumor group, but GPD1L and SMAD9 expression were dramatically decreased in control group (all P < 0.001)." (PMID 40796704, 2025). "TGFB1, TGFB3, NOG, and SMAD9, components of the TGF-β pathway, participate in tumor metastasis and cancer stem cells." (PMID 36344487, 2022). "Moreover, gene expression analysis showed that the expressions of KRT8 and S100A16 were significantly increased in tumor tissues, while the expressions of COL4A3, SMAD9, MAP3K8 and CCDC146 were decreased." (PMID 41239716, 2025). "Similarly, in the LUAD tumor group, HSPA6, NOTCH3, and PKP2 protein expression were dramatically stimulated, whereas GPD1L and SMAD9 protein expression were dramatically suppressed (all P < 0.05)." (PMID 40796704, 2025). "Studies have confirmed that SMAD9 also binds to the MYCN promoter to form a positive feedback loop, and gene silencing experiments have shown that SMAD9 knockout can significantly inhibit MNA-NB cell proliferation and tumor formation ability." (PMID 41244073, 2025).
tumor (continued). "In addition, the expression of serum HSPA6, NOTCH3 and PKP2 were significantly up-regulated in the LUAD tumor group, while GPD1L and SMAD9 showed a significant down-regulation trend when compared to the control group." (PMID 40796704, 2025). "Reverse transcription-quantitative polymerase chain reaction validation results demonstrated that KRT8 and S100A16 were significantly upregulated in tumor tissues, while COL4A3 and SMAD9 expression was downregulated, which was consistent with the TCGA-LUAD database analysis." (PMID 41239716, 2025). "CD3EAP, SMAD9, and CD244 are considered valuable tumor markers, with CD3EAP particularly noteworthy as a tumor marker in smokers." (PMID 39092217, 2024). "However, tumor growth promoted by H1299-EVs was inhibited by Smad9, while in the presence of BEAS-2B-EVs, overexpression of Smad9 reduced tumor growth in mice." (PMID 33472665, 2021). "Moreover, tumor weight and volume were higher in H1299-EV-treated mice but lower in mice treated with BEAS-2B-EVs + Smad9 than in BEAS-2B-EV-treated mice." (PMID 33472665, 2021). "However, gene cluster C showed higher expression of molecules (TGF-β2 and Smad9) related with TGF-β/EMT pathway than gene cluster A and B, indicating gene cluster C was deemed as stromal activated characteristic and tumor promotion." (PMID 36707884, 2023). "However, H1299-EVs failed to increase the tumor weight and volume in the tumors after Smad9 was stably overexpressed." (PMID 33472665, 2021). "Finally, while the five biomarker proteins (HSPA6, NOTCH3, PKP2, SMAD9, and GPD1L) are primarily intracellular, their presence in serum could potentially be attributed to tumor derived extracellular vesicles or cell lysis during tumor progression." (PMID 40796704, 2025).
cancer (17 papers, 2019 to 2025). A tumor composed of atypical neoplastic, often pleomorphic cells that invade other tissues. "We found that downregulation of SMAD9 in treated cancer patients was associated with poor survival and a low risk of death." (PMID 39940786, 2025). "There was a greater difference in the expression of SMAD2, SMAD3, SMAD4, SMAD5, and SMAD9 between cancer and normal samples." (PMID 38514720, 2024). "SMAD9 knockdown attenuated the transcriptomic phenotypes of MYCN-associated autonomous nervous system development and the cancer cell cycle." (PMID 36539767, 2022). "SMAD9 is involved in the progression of NSCLC by miR-744 delivered by cancer-derived extracellular vehicles." (PMID 36118863, 2022). "High SMAD9 expression was associated with MYCN-associated autonomous neural tumorigenicity and a robust cancer cell cycle." (PMID 36539767, 2022). "The four genes are associated with important cancer pathways, namely, the MAPK/PI3K pathways (FN1 and DUSP4), the Wnt pathway (LEF1), and the TGF pathway (SMAD9)." (PMID 34485158, 2021). "The involvement of SMAD9 in protein binding functions may underscore its role in modulating signaling pathways that are often dysregulated in cancer." (PMID 40796704, 2025). "Furthermore, signaling pathways at AD onset that were primarily addressed with CBD treatment (e.g., embryonic stem cell pluripotency, adipogenesis, proliferation and myelination, and molecular mechanisms of cancer) centered on Smad9." (PMID 40979532, 2025). "In NB, SMAD9 exhibited high expression among all cancer and normal cells." (PMID 36539767, 2022). "We performed an upstream regulatory analysis in SEdb to investigate the reason why SMAD9 was highly and specifically expressed in NB, showing that SMAD9 was a specific SEs-targeted gene in NB compared to other cancer types according to SE counts, SE rank and SE binding patterns." (PMID 36539767, 2022). "Here we performed an integrative analysis of public datasets and found that SMAD9 was characterized by specific high expression and dependence among all cancer types and was positively correlated with MYCN expression and a poor prognosis in high-risk NB patients." (PMID 36539767, 2022). "Further studies revealed that SMAD9 bound to the MYCN promoter and transcriptionally regulate MYCN expression, with MYCN reciprocally binding to the SMAD9 enhancer and transactivating SMAD9, thus forming a positive feedback loop along with the MYCN-associated cancer cell cycle." (PMID 36539767, 2022). "We then addressed whether cancer cell-derived EVs promoted NSCLC cell growth by regulating the Smad9/BMP4 pathway and thus, CCK-8 proliferation assay and colony formation assay were performed." (PMID 33472665, 2021). "Thus, cancer cell-derived EVs could upregulate BMP4 expression by suppressing Smad9 expression in NSCLC cells." (PMID 33472665, 2021). "Mechanistic studies showed that SMAD9 bound to the MYCN promoter, partially regulated MYCN expression and further mediated the cancer cell cycle." (PMID 36539767, 2022). "Overall, our findings unveiled a mechanism whereby miR-744 delivered by NSCLC-derived EVs upregulated SUV39H1, activating the Smad9/BMP9 axis and thus promoted cancer development." (PMID 33472665, 2021). "Stage 4 is characterized by high progression of cancer, and therefore, only SMAD3, SMAD5, and SMAD9 showed prognostic significance in this stage." (PMID 34138687, 2021). "SMAD9 and ENPP6 are both involved in bone mineralization and could be involved in cancer like the gene BMPR1A (bone mineralization protein 1A), where variants predispose to CRC." (PMID 39543761, 2024). "Thus, we speculated that reduced expression of miR-744 in cancer cell-derived EVs enhanced SUV39H1, which further suppressed the expression of Smad9 and consequently elevated the BMP4 expression, promoting the NSCLC progression." (PMID 33472665, 2021).
cancer (continued). "The rest four genes (YWHAG, ATXN1, UBQLN4, and SMAD9) also ranked high because of its high degree in transition probability W. Although they are not presented in CGC, some evidences show that these four candidate genes have functional roles in cancer or cancer-related biological processes." (PMID 31888623, 2019). "Although ATXN1, SMAD9, UBQLN4 and GRB2 are not included in CGC, we have already mentioned that ATXN1, SMAD9 and UBQLN4 are all relate to cancers or pathway in the last paragraph." (PMID 31888623, 2019).
infection (2 papers, 2016 to 2025). The state of being infected such as from the introduction of a foreign agent such as serum, vaccine, antigenic substance or organism. "Moreover, at least five transcription factors, such as the oncogene MYB, SMAD family members 6 and 9 (SMAD6 and SMAD9), and histone decetylase 5 (HDAC5), were significantly affected by infection in CHB." (PMID 27197554, 2016).
SMAD9 also shares sentences with these, for which no sentence is quoted: amyotrophic lateral sclerosis (2 papers); B-cell lymphoma (2); Duchenne muscular dystrophy (2); glioblastoma (2); granulosa cell tumor (2); Alport syndrome (1); astrocytomas (1); breast tumor (1); cardiovascular disease (1); Cognitive impairment (1); colitis (1); colorectal cancer (1); colorectal neoplasm (1); diabetic retinopathy (1); essential hypertension (1); fibrosarcoma (1); Hamartomatous polyposis (1); hepatocellular carcinoma (1); Infertility (1); ischemic stroke (1); kidney disease (1); liver fibrosis (1); lymph node metastasis (1); myeloid leukaemia (1); myopia (1); oligodendroglioma (1); Osteopenia (1); papillary thyroid carcinoma (1); peripheral nerve injury (1); premature ovarian failure (1).
A further 6 diseases each share a sentence with SMAD9 in 1 paper.